SEMG1 (semenogelin 1)
Description:
Predominant protein in semen. It participates in the formation of a gel matrix entrapping the accessory gland secretions and ejaculated spermatozoa. Fragments of semenogelin and/or fragments of the related proteins may contribute to the activation of progressive sperm movements as the gel-forming proteins are fragmented by KLK3/PSA. Alpha-inhibin-92 and alpha-inhibin-31, derived from the proteolytic degradation of semenogelin, inhibit the secretion of pituitary follicle-stimulating hormone.
Synonyms: SGI; SEMG; CT103; dJ172H20.2
Tractability: Antibody: its Gene Ontology location is reachable by antibodies, with high confidence; UniProt places it where antibodies can reach, with medium confidence; UniProt predicts a signal peptide or a membrane-spanning region.
Gene: Protein-coding gene on chromosome 20 (45,207,033 to 45,210,605, forward strand). Ensembl gene ENSG00000124233.
Subcellular location: Secreted
Pathways (Reactome):
Immune System: Antimicrobial peptides
Metabolism of proteins: Amyloid fiber formation
Gene Ontology:
Molecular function: extracellular matrix structural constituent; protein binding; zinc ion binding
Biological process: antibacterial humoral response; antimicrobial humoral immune response mediated by antimicrobial peptide; coagulation; killing of cells of another organism; negative regulation of calcium ion import; negative regulation of flagellated sperm motility; positive regulation of serine-type endopeptidase activity; insemination; sperm capacitation
Cellular component: extracellular exosome; extracellular region; nucleus; protein-containing complex; acrosomal vesicle
Genetic constraint (gnomAD): Loss-of-function variants: 6 observed, 9.38 expected, observed/expected ratio (o/e) 0.64, 90% interval 0.35 to 1.26. That is too few expected variants to judge how well the gene tolerates losing a copy. Missense variants: 579 observed, 549.08 expected, observed/expected ratio (o/e) 1.05, 90% interval 0.98 to 1.13. Synonymous variants: 221 observed, 196.49 expected, observed/expected ratio (o/e) 1.12, 90% interval 1.01 to 1.26.
Homologues: Orthologues: chimpanzee SEMG1 (89% identical), rat Semg1 (17% identical), mouse Semg1 (16% identical), rat Svs3a (13% identical), rat Svs3b (13% identical), mouse Svs3b (11% identical), mouse Svs3a (11% identical). Paralogues in human: SEMG2 (78% identical).
Diseases named in the same sentence as SEMG1 in open-access papers:
SEMG1 is named in the same sentence as 29 diseases in open-access papers, as found by Europe PMC text mining. Sharing a sentence is not in itself a finding about the gene and the disease. The quoted sentences say what the papers report.
Infertility (9 papers, 2017 to 2024). "In conclusion, although our samples were limited, our finding suggested that down-and up-regulation of the CRISP2 and SEMG1 respectively was associated with the idiopathic AZS infertile men." (PMID 31058050, 2019). "For instance, it would be interesting to investigate if SEMG1 (Svs2 in mice), the gene encoding semenogelin 1, is up-methylated and silenced in association with the symptom of decreased sperm motility in infertile patients." (PMID 28085963, 2017). "Genetic alterations of SEMG1 variant rs147894843 is involved in altered proteolytic activity, which may affect semen quality and liquefaction leading to infertility in men." (PMID 32529252, 2020). "In Chinese–Han male population, the SEMG1 variant rs2301366 was associated with abnormal semen parameters such as semen volume, sperm concentration, sperm number per ejaculate, and sperm motility and more susceptible to infertility." (PMID 32529252, 2020). "Importantly, our retrospective follow‐up study showed that both low miR‐525‐3p expression and high SEMG1 expression level was significantly associated with low progressive sperm motility, abnormal sperm morphology, and infertility." (PMID 30575326, 2019). "Meanwhile, a follow‐up study of reproductive history indicated that both low expression of miR‐525‐3p and high expression of SEMG1 were correlated with low progressive sperm motility, abnormal morphology, and infertility, respectively." (PMID 30575326, 2019). "It is interesting to note that the infertility rate in AZS patients was higher while high infertility rate was closely related to high SEMG1 or low miR‐525‐3p expression." (PMID 30575326, 2019). "This protein degrades SEMG1 and SEMG2 during the transfer of spermatozoa to the female reproductive tract, and its inactivation in seminal plasma could be linked to infertility." (PMID 38654926, 2024). "Anti-EPPIN antibodies bound to sperm substitute for SEMG1 and result in reversible infertility." (PMID 29672554, 2018). "In the present study, proteomic profile of seminal plasma showed both SEMG1 and SEMG2 were underexpressed in primary and secondary infertile men compared to control group." (PMID 32372034, 2020). "Increased seminal plasma levels of SEMG1 and SEMG2 have been reported in men with infertility." (PMID 38654926, 2024). "Both SEMG1 and SEMG2 have been reported to be downregulated in infertile men." (PMID 38028760, 2023). "Failure to remove SEMG1 due to a lack of PSA activity results in seminal hyper-viscosity and infertility." (PMID 29672554, 2018).
varicocele (6 papers, 2015 to 2025). A condition characterized by the dilated tortuous veins of the spermatic cord with a marked left-sided predominance. "SEMG1 preprotein was underexpressed in the unilateral varicocele patients with a high abundance when compared with the healthy fertile men." (PMID 25890347, 2015). "Among the altered proteins, several exosomal proteins including Annexin A2 (ANXA2), Transferrin (TF), Kinesin‐1 heavy chain (KIF5B), and semenogelin 1 (SEMG1) were found to be consistently expressed differently in the seminal plasma of patients with unilateral varicocele." (PMID 41222141, 2025). "Other proteins associated with normal sperm functions, such as SEMG1 and SEMG2, acrosin (ACR), elongation factor 1-gamma (EEF1G) and PGK2 were downregulated in SP from varicocele, probably explaining the poor sperm motility and concentration usually found in these patients." (PMID 32987677, 2020). "Specifically, there was an overexpression of SEMG1 and an underexpression of KLK3 and ACPP in the SP of varicocele patients." (PMID 32987677, 2020). "Notable proteins include calcium-binding tyrosine phosphorylation-regulated protein (CABYR), A-kinase anchor proteins (AKAP), APOA1, semenogelin-1 (SEMG1), and sperm surface protein Sp17 (SPA17), which have been highlighted as potential biomarkers for unilateral varicocele." (PMID 39685846, 2024). "Additionally, proteins such as enkurin (ENKUR), semenogelin-1 and -2 (SEMG1/2), sperm adhesion molecule 1 (SPAM1), and CABYR serve as indicators of reduced semen quality in bilateral varicocele patients." (PMID 39685846, 2024). "CABYR, SEMG-1 preproprotein, RSPH1and SPA17 were underexpressed in the unilateral varicocele group." (PMID 25890347, 2015). "Some of the more abundant proteins in the unilateral varicocele group were lactotransferrin isoform 1 precursor (LTF), fibronectin isoform 3 preprotein (FN1), semenogelin-2 precursor (SEMG2), A-kinase anchor protein 4 isoform 2 (AKAP4), and semenogelin-1 preprotein (SEMG1)." (PMID 25890347, 2015).
asthenozoospermia (4 papers, 2019 to 2022). "Prostate specific antigen-mediated cleavage of SEMG1 yields functional polypeptides that favor semen liquefaction and enhanced sperm motility, and increased sperm levels of SEMG1 are often associated with asthenospermia." (PMID 33423702, 2021). "SEMG1 is the semenogelin 1 gene, expressed mainly on the prostate and is suggested to be responsible for asthenozoospermia." (PMID 35057575, 2022). "The purpose of this study was to analyze the expression level of CRISP2, CATSPER1, PATE1 and SEMG1 genes in the sperm of men with asthenozoospermia (AZS)." (PMID 31058050, 2019). "Previous studies show that the SEMG1 gene is highly expressed in spermatozoa from patients with asthenozoospermia (AZS); however, the underlying molecular mechanisms are not yet clear." (PMID 30575326, 2019). "Furthermore, our previous study has identified SEMG1 as a potential marker for idiopathic asthenozoospermia." (PMID 30575326, 2019).
prostate carcinoma (3 papers, 2021 to 2024). A carcinoma that arises from epithelial cells of the prostate gland. "Protein expression analyses have revealed that SEMG1 is mostly expressed in the glandular epithelium of seminal vesicles and some studies have demonstrated their expression in prostate cancer cells." (PMID 36550367, 2022). "An exception is the only study in which SEMG1 was shown as co-activator of the androgen receptor in prostate cancer which protects cancer cells from zinc-mediated cytotoxicity." (PMID 33966049, 2021). "The expression of SEMG1 in prostate cancer can be associated with both positive and negative patient survival." (PMID 33966049, 2021). "Taking into account our data about SEMGs’ features in several cancer cell models, literature data about biological activity of SEMG1 in prostate cancer and the known biological role of SEMGs in reproduction, we hypothesize that SEMGs expression can have an impact on malignant cells." (PMID 33966049, 2021). "Genes in peptidase activity pathways, including SEMG1 and SEMG2, were significantly upregulated in prostate cancer from AA men." (PMID 38566104, 2024). "Thus, literature data indicates the potential difference in the functions of SEMG1 and SEMG2 in prostate cancer." (PMID 33966049, 2021).
Azoospermia (1 paper, 2021). Absence of any measurable level of sperm,whereby spermatozoa cannot be observed even after centrifugation of the semen pellet. "Additionally, germ cell-specific (DEAD-box helicase 4), seminal vesicle-specific (Semenogelin 1), and prostate-specific (Transglutaminase 4) mRNAs in seminal plasma could be markers for identifying the presence of germ cells or the rough localization of complete obstructive azoospermia." (PMID 35211476, 2021).
breast carcinoma (1 paper, 2020). "Moreover, we also examined MDA-MB-468 and MCF7 breast cancer cell lines transiently transfected with either SEMG1, SEMG2, or an empty vector as control for the ROS production." (PMID 33311447, 2020). "To extend our observations, we examined for MMP two additional breast cancer cell lines, MDA-MB-468 (Fig. 4A_Suppl) and MCF7 (Fig. 5A_Suppl), transiently transfected with SEMG1 or SEMG2 vectors." (PMID 33311447, 2020).
chronic leukemia (1 paper, 2023). A slowly progressing leukemia characterized by a clonal (malignant) proliferation of maturing and mature myeloid cells or mature lymphocytes. "Noteworthy, PRM1 was reported to be interacted with SEMG1 in chronic leukemia, which implied the functional relevance between PRM1 and SEMG1." (PMID 36593375, 2023).
cystinuria (1 paper, 2017). Cystinuria is a renal tubular amino acid transport disorder characterized by recurrent formation of kidneys cystine stones. "Up-regulated genes included several genes (SLC7A9, SEMG1, SBSPON and MEGF6) that were not well functionally characterized (except SLC7A9, a marker for cystinuria) and are not discussed here." (PMID 29284484, 2017).
disordered eating (1 paper, 2022). "We performed SMR to capture this in our analysis and found an association of disordered eating with CpG sites on SETBP1 and SEMG1." (PMID 35057575, 2022).
epilepsy (1 paper, 2024). A brain disorder characterized by episodes of abnormally increased neuronal discharge resulting in transient episodes of sensory or motor neurological dysfunction, or psychic dysfunction. "Surprisingly, we also identified many differential proteins such as UGGT2, SEMG1, PDIA4, ROR1, NIF3L1, and ITIH4, that have not previously been directly reported with epilepsy." (PMID 38585359, 2024).
lung carcinoma (1 paper, 2020). "Both SEMGs are expressed in all types of lung cancer cell lines tested but the mRNA level of SEMG1 in general was higher than that of SEMG2." (PMID 33311447, 2020). "High levels of SEMG1 and SEMG2 expression are detected in prostate, renal, and lung cancer as well as hemoblastosis." (PMID 33311447, 2020).
male infertility (1 paper, 2019). The inability of the male to effect fertilization of an ovum after a specified period of unprotected intercourse. "Further clinical correlation analysis and follow‐up studies of the reproductive history of study patients suggested that elevated SEMG1 and reduced miR‐525‐3p levels are associated with AZS and male infertility." (PMID 30575326, 2019). "The relationship between high SEMG1 mRNA or low miR‐525‐3p and male infertility was found in our follow‐up study of reproductive history." (PMID 30575326, 2019). "The elevated expression of SEMG1 and reduced expression of miR‐525‐3p are associated with AZS and male infertility." (PMID 30575326, 2019). "Our findings demonstrate that the deletion of miR‐525‐3p contributes to the aberrant expression of SEMG1, clinically involving in AZS and male infertility, which provides a potential therapeutic target for the treatment of male infertility and for male contraception." (PMID 30575326, 2019). "Though there may be more unidentified regulatory mechanisms that may contribute to AZS and sterility, our research first demonstrates that miR‐525‐3p deletion may contribute to aberrant expression of SEMG1, clinically involving in AZS and male infertility." (PMID 30575326, 2019).
melanoma (1 paper, 2020). A malignant, usually aggressive tumor composed of atypical, neoplastic melanocytes. "Meanwhile, profiles of expression of HAGE, PASD1, SEMG1, SLLP1, SPANXA1, SSX1 weren’t significantly different in STBS and melanoma cell cultures at the complex assessment." (PMID 32042403, 2020).
multiple myeloma (1 paper, 2022). "As an example, Semenogelin 1 (SEMG1) expression is positively correlated with the presence of interleukins (IL-4 and IL-6) in multiple myeloma cells." (PMID 37529004, 2022).
non-small cell lung carcinoma (1 paper, 2020). A group of at least three distinct histological types of lung cancer, including non-small cell squamous cell carcinoma, adenocarcinoma, and large cell carcinoma. "We demonstrate here that SEMG1 and SEMG2 (SEMGs) exhibit different patterns of expression and sub-cellular localization in non-small cell lung cancer (NSCLC) cell lines." (PMID 33101710, 2020).
oral mucositis (1 paper, 2025). Inflammation of the mucous membranes of any of the structures in the mouth. "As the only exception, three putative autoantibodies were significantly higher in “mucosal toxicity” compared with “no toxicity” (PCBP2, COL6A1, SEMG1), referring to patients developing oral mucositis." (PMID 40449958, 2025).
renal carcinoma (1 paper, 2021). A carcinoma arising from the epithelium of the renal parenchyma or the renal pelvis. "However, there is evidence of a positive association between SEMG1 level and a patient’s survival in case of renal carcinoma." (PMID 33966049, 2021).
small cell lung carcinoma (1 paper, 2020). Small cell lung cancer (SCLC) is a highly aggressive malignant neoplasm, accounting for 10-15% of lung cancer cases, characterized byrapid growth, and early metastasis. "Besides, SEMG1 and SEMG2 were detected in various malignancies including small cell lung cancer (SCLC)." (PMID 33101710, 2020).
squamous cell carcinoma (1 paper, 2020). A carcinoma arising from squamous epithelial cells. "However, we demonstrate here the ubiquitous presence of SEMG2 in all NSCLC cell lines tested whereas SEMG1 was detected in three out of five cell lines: in H520 squamous carcinoma and in two adenocarcinoma (H522 and H1650) cell lines." (PMID 33101710, 2020). "To expand our knowledge on SEMGs expression in NSCLCs on the protein level, we decided to check the presence of highly homologous SEMG1 and SEMG2 proteins in the panel of 5 adenocarcinoma and 1 squamous cell carcinoma NSCLC cell lines." (PMID 33101710, 2020).
cancer (6 papers, 2016 to 2024). A tumor composed of atypical neoplastic, often pleomorphic cells that invade other tissues. "To assess in details the influence of SEMGs on energy metabolism of cancer cells we have carried out the SeaHorse profiling of Mia-Paca2 cell line overexpressing SEMG1, SEMG2, or control vector." (PMID 33311447, 2020). "In the present work, we have shown that SEMG1 and SEMG2 are observed at different frequencies in various human cancer cell lines and are associated with poor prognosis for survival of patients." (PMID 33311447, 2020). "Information about the biological activity of SEMGs in cancer is also limited and only describes SEMG1 as a co-activator of androgen receptor in prostate cancer." (PMID 33311447, 2020). "SEMG1, CLU and GSN have been reported to be associated with cancers." (PMID 38763993, 2024). "Since both SEMG1 and SEMG2 affected the activity of crucial metabolic enzymes of glycolysis, we next decided to assess whether these proteins can regulate the cancer-related metabolism because glycolysis is a well-known hallmark of cancer." (PMID 33311447, 2020). "Semenogelin 1 (SEMG1) and SEMG2 interact with pyruvate kinase M2 and lactate dehydrogenase A to promote glycolysis and respiration in various cancer cell lines." (PMID 37834126, 2023). "Taken together, these results suggest that both SEMG1 and SEMG2 enhance the fluorescence intensity of MitoTracker, hence reflecting an increase of MMP and possible cancer aggressiveness." (PMID 33311447, 2020). "Taken together, our data demonstrate that two autosomal CTAs, SEMG1 and SEMG2, are frequently expressed in human malignancies and enhance energy metabolism of cancer cells." (PMID 33311447, 2020). "Taken together, these data clearly demonstrate that SEMG1 and SEMG2 enhance energy metabolism of cancer cells." (PMID 33311447, 2020). "The functions of SEMGs (mainly SEMG1) are known only in reproduction, and information on the functions of SEMGs in malignant neoplasms is particularly absent." (PMID 33966049, 2021).
tumor (6 papers, 2020 to 2024). "In addition, an inverse association was observed between the expression of SEMG1 and the stage of tumor development." (PMID 33966049, 2021). "Collectively, our data suggest tumor suppressive properties of SEMG1 and SEMG2 in model H1299 lung adenocarcinoma cells." (PMID 33101710, 2020). "Of the six genes (IGF2BP1, GPRC6A, IL37, CRCT1, SEMG1, and PSG7) for which we analyzed the differential expression between tumor tissues and healthy tissues in TCGA, four genes (CRCT1, PSG7, IL37, and IGF2BP1) showed notable differences." (PMID 36276966, 2022). "It is feasible that these peptide regions could be responsible for interacting with PSA substrates, like semenogelin-1 and 2, or could be related to PSA acting extracellularly in the tumor microenvironment to proteolytically modify the ECM." (PMID 39347566, 2024). "The mRNA levels of SEMG1 and SEMG2 in tumor samples were higher than in peritumoral tissues." (PMID 33311447, 2020).
adenocarcinoma (2 papers, 2020). A common cancer characterized by the presence of malignant glandular cells. "Nevertheless, at least in our adenocarcinoma cancer cell model, we have shown that overexpression of both SEMG1 and SEMG2 elevated ROS production two-fold." (PMID 33101710, 2020). "SEMG1 and SEMG2 were expressed in H520 adenocarcinoma cell lines but not in normal human fibroblasts." (PMID 33311447, 2020).
neurodegenerative disease (1 paper, 2025). A disorder of the central nervous system characterized by gradual and progressive loss of neural tissue and neurologic function. "A high abundance of WNT, SEMG1, PSMB3, PSMC5, and other proteins in the advanced age group may be associated with risk for neurodegenerative diseases, malignancies, and impact sperm DNA integrity, spermatozoa survival and function, and fertilization." (PMID 40649876, 2025).
SEMG1 also shares sentences with these, for which no sentence is quoted: infection (1 paper); osteosarcoma (1); pancreatic adenocarcinoma (1); pancreatic cancer (1); sarcoidosis (1); sterility (1).